HOTAIR (HOX transcript antisense RNA)
Diseases named in the same sentence as HOTAIR in open-access papers (continued):
Sharing a sentence is not in itself a finding about the gene and the disease.
atherosclerosis (12 papers, 2017 to 2025). A disease characterized by the build-up of fatty material and calcium deposition in the arterial wall resulting in partial or complete occlusion of the arterial lumen. "Our findings provide valuable insights into the molecular mechanisms underlying the involvement of HOTAIR in atherosclerosis." (PMID 38250607, 2024). "Collectively, our study highlights HOTAIR as a promising therapeutic target for attenuating foam cell formation and mitigating the inflammatory response associated with atherosclerosis." (PMID 38250607, 2024). "Regarding the association between HOTAIR and metabolic disorders or related co-morbidities, low expressions of HOTAIR in peripheral blood lymphocytes were observed in patients with atherosclerosis." (PMID 36361470, 2022). "Identifying HOTAIR as a critical regulator in atherosclerosis further highlights the importance of lncRNAs in CVDs." (PMID 38250607, 2024). "Overall, our study provides novel insights into the regulatory role of HOTAIR in atherosclerosis and highlights its potential as a therapeutic target for modulating lipid uptake and inflammatory responses in foam cell formation." (PMID 38250607, 2024). "To investigate the expression of HOTAIR in individuals with atherosclerosis, we assessed its levels in plasma samples obtained from 100 atherosclerosis patients and 100 healthy controls." (PMID 38250607, 2024). "By integrating our current findings with previous studies, we have uncovered the role of HOTAIR in atherosclerosis." (PMID 38250607, 2024). "Our results suggest that HOTAIR plays a significant part in alleviating foam cell formation and reducing the inflammatory response in the context of atherosclerosis." (PMID 38250607, 2024). "Specifically, we demonstrate that HOTAIR plays a role in alleviating foam cell formation and suppressing the inflammatory response by inhibiting miR-19a-3p in the context of atherosclerosis." (PMID 38250607, 2024). "Circulating lncRNAs have become potential biomarkers of atherosclerosis in diagnostic, prognostic, and predictive tools, such as ZFAS1, HOTAIR, MALAT1." (PMID 37371830, 2023). "For example, in ox-LDL induction in Raw264.7 cells (in vitro atherosclerosis model), HOTAIR overexpression reduced the inflammatory response and by NF-κB pathway by regulating FXR1." (PMID 35813070, 2022). "Two of the target genes shown to be affected by HOTAIR knockdown, SIRT2 and LRP1B, have been implicated in atherosclerosis." (PMID 30893946, 2019). "The expression of HOTAIR is decreased in sporadic thoracic aortic aneurysm tissue, ECs for atherosclerotic plaques, and in the peripheral blood lymphocytes of atherosclerosis patients, but increased in patients with diabetes and congenital heart disease." (PMID 30893946, 2019). "As inflammation is an important aspect of atherosclerosis, the function of HOTAIR has been studied in monocyte/macrophage cell lines." (PMID 30893946, 2019). "In the present study, we analyzed the expression pattern of HOTAIR in EC of atherosclerosis and detected its effect on EC proliferation, apoptosis and migration." (PMID 28615347, 2017). "First, we examined the expression pattern of HOTAIR in EC isolated from atherosclerotic plaque in atherosclerosis patients." (PMID 28615347, 2017). "However, the specific role of HOTAIR in the pathogenesis of atherosclerosis has yet to be determined." (PMID 38250607, 2024). "By targeting the miR-19a-3p-HBP1-MIF pathway, HOTAIR represents a potential therapeutic target for modulating the inflammatory response and foam cell formation, offering promising avenues for the development of novel treatments for atherosclerosis." (PMID 38250607, 2024). "Our analysis revealed a significant downregulation of HOTAIR in patients with atherosclerosis." (PMID 38250607, 2024).
atherosclerosis (continued). "Combined with present and previous studies, we uncovered the involvement of HOTAIR in atherosclerosis, at least in part, we demonstrate that HOTAIR alleviates the formation of foam cell and inflammatory reaction by inhibiting miR-19a-3p in atherosclerosis through TNF-α/miR-19a/HBP1/MIF pathway." (PMID 38250607, 2024). "Our findings revealed that HOTAIR expression was downregulated in patients with atherosclerosis." (PMID 38250607, 2024). "Our previous research elucidated the role of miR-19a-3p in atherosclerosis through the miR-19a/HBP1/MIF pathway upon that foundation, the current study aimed to investigate the expression levels of HOTAIR in both the plasma of atherosclerosis patients and foam cells." (PMID 38250607, 2024). "This indicated that HOTAIR may serve as a treatment target for preventing and treating atherosclerosis." (PMID 35813070, 2022). "Moreover, in atherosclerosis patients, serum level of thymic stromal lymphopoietin was lower and positively correlated with HOTAIR expression in endothelial cells, suggesting a potential therapy for endothelial dysfunction in atherosclerosis." (PMID 32630452, 2020). "Moreover, serum levels of thymic stromal lymphopoietin (TSLP), belonging to IL-7 like cytokine family, decrease in atherosclerosis patients, and positively correlates with HOTAIR expression in endothelial cells." (PMID 31072041, 2019). "Interestingly, we observed several well-known lncRNAs, such as TUG1, PCA3, and HOTAIR, which were also involved in regulating atherosclerosis progression." (PMID 30873207, 2019). "In addition, we analyzed the correlation between serum TSLP level and HOTAIR expression of EC in atherosclerosis patients." (PMID 28615347, 2017). "A positive correlation between serum TSLP level and HOTAIR expression of EC in atherosclerosis patients was observed (r2 =0.6702, P<0.0001), indicating that HOTAIR expression may be regulated by TSLP." (PMID 28615347, 2017). "However, the functional role of HOTAIR in EC of atherosclerosis and whether HOTAIR is regulated by TSLP-induced activation of AKT pathway remains unclear." (PMID 28615347, 2017). "TSLP and HOTAIR may serve as a novel therapy for atherosclerosis." (PMID 28615347, 2017). "This lncRNA also plays a role in atherosclerosis by downregulating miR-19a-3p through HOTAIR overexpression and observing a negative correlation in the plasma of patients with atherosclerosis, and reducing the foam cell formation and inflammatory reaction." (PMID 40801625, 2025). "In addition, we observed that serum TSLP level was much lower in atherosclerosis and there existed a positive correlation between TSLP and HOTAIR expression." (PMID 28615347, 2017). "Notably, there was a negative correlation between the expression of HOTAIR and miR-19a-3p in the plasma of the 100 atherosclerosis patients." (PMID 38250607, 2024). "HOTAIR served as a scaffold for histone modification complexes PRC-2 and LDS-1, facilitating epigenetic histone modifications, and its overexpression could reduce endothelial dysfunction in atherosclerosis." (PMID 35906216, 2022). "In a non-neoplastic model, a recent study showed that HOTAIR is down-regulated in endothelial cells isolated from atherosclerotic plaque in atherosclerosis patients compared with corresponding vascular wall, suggesting that HOTAIR plays a protective role for endothelial cells injury." (PMID 31072041, 2019).
small cell lung carcinoma (12 papers, 2014 to 2025). Small cell lung cancer (SCLC) is a highly aggressive malignant neoplasm, accounting for 10-15% of lung cancer cases, characterized byrapid growth, and early metastasis. "For example, HOTAIR plays an important role in cellular proliferation, invasion, and clinical relapse in small cell lung cancer." (PMID 31696057, 2019). "The hypermethylation of HOXA1 may be regulated by H3K27me3 through HOTAIR, thereby contributing to the development of chemoresistance in small-cell lung cancer (SCLC)." (PMID 38311789, 2024). "HOTAIR was upregulated in the DOX-resistant small cell lung cancer cell (SCLC)." (PMID 37781691, 2023). "In small-cell lung cancer, HOTAIR could induce HOXA1 methylation and lead to multidrug resistance through the NF-κB pathway." (PMID 36471329, 2022). "In small cell lung cancer (SCLC), HOTAIR was found to inhibit expression of DNMT1 and DNMT3B, thus regulating the methylation of HOXA1 to mediate chemoresistance of SCLC." (PMID 36533073, 2022). "Ranked No. 5 is HOTAIR, and the literature found that HOTAIR affects the drug resistance of small cell lung cancer cells by regulating the methylation of HOXA1." (PMID 33794766, 2021). "Finally, a recent study analyzed HOTAIR expression in typical carcinoid tumors, atypical carcinoid tumors, small cell lung carcinoma (SCLC/NEC) and large cell neuroendocrine carcinoma (LCNEC/NEC), highlighting its upregulation only in SCLC/NEC patients." (PMID 34576322, 2021).
diabetes (11 papers, 2018 to 2024). "HOTAIR is a critical lncRNA in inflammatory diseases, including gout, ischemia-reperfusion injury, and diabetes, and is associated with oxidative stress, cytokines release, and apoptosis." (PMID 37713847, 2023). "In order to confirm the synergistic effects of clinical factors and genotypes, we performed stratified analysis based on the classification of sex, age, hypertension, diabetes mellitus, plasma folate, and homocysteine levels analyzed the interactions with HOTAIR polymorphisms." (PMID 32117729, 2020). "Therefore, HOTAIR gene polymorphisms might be a predictor for other types of diabetes or related complications." (PMID 35359879, 2022). "In our prior investigation regarding the effect of lncRNAs in the context of diabetes, we found that HOTAIR rs920778, rs12826786, and rs4759314 SNPs had a significant correlation with T2DM." (PMID 38958113, 2024). "On the other hand, the overexpression of HOTAIR protected against diabetes‐induced cardiac hypertrophy and dysfunction." (PMID 33639953, 2021). "A functional role for HOTAIR in the diabetes pathogenesis is yet to be established; however, its role has been hinted to be associated with regional adiposity." (PMID 30139387, 2018). "However, to this day, not a single study has reported the link between functional gene variations in HOTAIR and other types of diabetes." (PMID 35359879, 2022). "In silico analyses predicted that HOTAIR is involved in various diabetes mellitus-related pathways, including apoptotic cell death, tumor necrosis factor (TNF), ras-mitogen-activated protein kinase (MAPK), forkhead box O (FoxO), and hypoxia-inducible factor 1 (HIF1)." (PMID 35359879, 2022). "Additionally, HOTAIR overexpression has been shown to protect against inflammation and oxidative stress induced by diabetes via the HOTAIR/miR-34a/SIRT1 axis." (PMID 34298896, 2021). "Nevertheless, the durations of diabetes in different HOTAIR SNPs rs1899663 showed insignificant differences throughout the whole diabetes population, non-DR group, NPDR subgroup, and PDR subgroup." (PMID 36361470, 2022). "In another study, the downregulated expression of HOTAIR was identified in both myocardial tissue and serum from patients with diabetic cardiomyopathy compared to patients with diabetes without cardiomyopathy and healthy controls." (PMID 34298896, 2021).
chondrosarcoma (10 papers, 2017 to 2021). A malignant cartilaginous matrix-producing mesenchymal neoplasm arising from the bone and soft tissue. "HOTAIR mediates cell growth by negatively regulating miR-454-3p expression in chondrosarcoma cells, through an EZH2-mediated mechanism." (PMID 33540611, 2021). "In chondrosarcoma patients, the expression of HOTAIR is correlated with tumor stage and poor prognosis." (PMID 34576322, 2021). "HOTAIR expression was increased in chondrosarcoma tissues compared with normal cartilage tissues and its aberrant expression was elevated in high-grade compared with low-grade chondrosarcoma tissues." (PMID 34576322, 2021). "HOTAIR knockdown results in growth inhibition of chondrosarcoma cells via miR-454-3p upregulation and Stat3 signaling inactivation in vivo." (PMID 33540611, 2021). "Upregulation of HOTAIR lncRNA has been observed in chondrosarcoma and chondrosarcoma cell lines (including soft-tissue-derived forms such as mesenchymal and myxoid chondrosarcoma), correlated with tumor stage and with a severe prognosis." (PMID 34207243, 2021). "HOTAIR knockdown led to growth inhibition via G0/G1 arrest and apoptosis in vitro and in vivo models of chondrosarcoma." (PMID 34576322, 2021). "HOTAIR knockdown impeded chondrosarcoma progression in vitro and in vivo through inhibiting autophagosome formation by downregulating ATG12." (PMID 33050642, 2020). "HOTAIR expression was up-regulated in chondrosarcoma tissues and cell lines, which induced DNA methylation of miR-454-3p by recruiting EZH2 and DNMT1 to the miR-454-3p promoter regions to silence miR-454-3p expression." (PMID 30266744, 2018). "Through the HOTAIR-miR-454-3p-STAT3/ATG12 axis, HOTAIR knockdown-induced inhibition of autophagy indirectly promoted chondrosarcoma cell apoptosis." (PMID 30266744, 2018). "Downregulation of HOTAIR resulted in growth inhibition of human chondrosarcoma cells via G0/G1 arrest and apoptosis." (PMID 28353666, 2017). "Many studies have shown that HOTAIR is physically associated with EZH2.34, 35, 36 In our study, EZH2 was upregulated in both chondrosarcoma cells and specimens, and knockdown of HOTAIR led to repression of EZH2." (PMID 28182000, 2017). "Functional experiments reveal that HOTAIR knockdown leads to growth inhibition of human chondrosarcoma cells in vitro and in vivo." (PMID 28182000, 2017). "Our analysis of cell cycle assay revealed that chondrosarcoma cells were mostly arrested in the G0/G1 phase, implying that there was a reduction in the number of dividing tumor cells following the knockdown of HOTAIR." (PMID 28182000, 2017). "Statistically, significant inverse interrelations were observed between HOTAIR and miR-454-3p expression in chondrosarcoma tissues." (PMID 28182000, 2017). "We also found that HOTAIR expression was increased in chondrosarcoma tissues compared with normal cartilage tissues." (PMID 28182000, 2017). "Taken together, this study reveals for the first time that miR-454-3p increases after HOTAIR knockdown to inhibit chondrosarcoma cell growth by targeting Stat3 and Atg12." (PMID 28182000, 2017). "Quantitative RT-PCR demonstrated that HOTAIR expression was upregulated in chondrosarcoma tissues and cell lines." (PMID 28182000, 2017). "According to our data, miR-454-3p is downregulated in chondrosarcoma tissues compared with normal cartilage tissues and is inversely correlated with HOTAIR expression in chondrosarcoma tissues." (PMID 28182000, 2017). "Altogether, these data demonstrate that HOTAIR is vital for chondrosarcoma cell survival and downregulation of HOTAIR leads to tumor cell apoptosis." (PMID 28182000, 2017). "In chondrosarcoma, elevated expression of HOTAIR predicted advanced tumor stage and poor survival." (PMID 33050642, 2020). "Knockdown of HOTAIR led to growth inhibition of human chondrosarcoma cells in vitro and in vivo." (PMID 28353666, 2017). "Downregulation of HOTAIR induced LC3 accumulation in chondrosarcoma cells." (PMID 28182000, 2017).
chondrosarcoma (continued). "The expression of HOTAIR was upregulated in chondrosarcoma tissues and cell lines." (PMID 28353666, 2017). "Collectively, our data reveal the roles and functional mechanisms of HOTAIR in human chondrosarcoma and suggest that HOTAIR may act as a prognostic biomarker and potential therapeutic target for chondrosarcoma." (PMID 28182000, 2017). "Next, we examined the correlation between HOTAIR expression and chondrosarcoma patient prognosis." (PMID 28182000, 2017). "Our data verified that HOTAIR was overexpressed in chondrosarcoma specimens and cell lines." (PMID 28182000, 2017). "Moreover, downregulation of HOTAIR inhibited autophagy, thereby promoting apoptosis in chondrosarcoma." (PMID 28182000, 2017). "Moreover, HOTAIR expression was higher in high-grade (grades II+III) chondrosarcoma tissues compared with low-grade (grade I) chondrosarcoma tissues." (PMID 28182000, 2017). "To determine whether HOTAIR is essential for chondrosarcoma cell survival and proliferation, we transfected three siRNA sequences targeting HOTAIR (siHOT) or scrambled siRNA (siNC) into HCS-2/8 and SW1353 cells." (PMID 28182000, 2017). "However, the function and potential biological mechanisms of HOTAIR in human chondrosarcoma remain unknown." (PMID 28182000, 2017). "HOTAIR is able to induce DNA methylation of miR-454-3p by recruiting EZH2 and DNMT1 in chondrosarcoma cells." (PMID 34576322, 2021). "HOTAIR sponged miR-454-3p and indirectly upregulated ATG12 to promote cancer progression in chondrosarcoma cells." (PMID 33050642, 2020). "In this study, we found that expression of miR-454-3p increased after HOTAIR knockdown, and we found that HOTAIR recruited EZH2 and DNMT1 to the promoter of miR-454-3p, increased DNA methylation at the miR-454-3p promoter regions and repressed miR-454-3p expression in chondrosarcoma." (PMID 28182000, 2017).
head and neck squamous cell carcinoma (10 papers, 2017 to 2024). A squamous cell carcinoma that arises from any of the following anatomic sites: lip and oral cavity, nasal cavity, paranasal sinuses, pharynx, larynx, and salivary glands. "It plays the same role in cancer, just like the HOTAIR / miR-206 / STC2 axis in head and neck squamous cell carcinoma." (PMID 36115953, 2022). "Although research on lncRNAs for head and neck squamous cell carcinoma is limited, a recent study has reported few differentially expressed lncRNAs such as HOTAIR, NEAT1, UCA1, and MALAT1, in oral cancers." (PMID 30002503, 2018). "It has been demonstrated that HOTAIR was up-regulated in cancer tissues, especially in head and neck squamous cell carcinoma (HNSCC)." (PMID 29228709, 2017). "In head and neck squamous cell carcinoma (HNSCC), STAT3 promotes the transcription of lncRNA HOTAIR and its interaction with pEZH2-S21, which contributes to resistance against both CDDP and cetuximab." (PMID 39403599, 2024). "A negative association has been reported between HOTAIR expression and the proportion of MDSCs in the blood samples of patients with human papillomavirus-positive head and neck squamous cell carcinoma (HPV-positive HNSCC), but a causal relationship has not been established." (PMID 31404149, 2019).